NOS2 (nitric oxide synthase 2)
Diseases named in the same sentence as NOS2 in open-access papers (continued):
Sharing a sentence is not in itself a finding about the gene and the disease.
infection (298 papers, 2007 to 2026). The state of being infected such as from the introduction of a foreign agent such as serum, vaccine, antigenic substance or organism. "This is aptly illustrated in NOS2-deficient mice, where infection with IAV was associated with reduced mortality, morbidity, and decreased cytokine production in the lung." (PMID 37437040, 2023). "NOS2, a gene associated with inflammation, infection control, and immune regulation, was found to be the top negative feature of PC1 (downregulated)." (PMID 37688629, 2023). "Functional inhibition led to an overexpression of Nos2/NOS2, which plays a key role in the macrophage polarization and leads to susceptibility to the infection." (PMID 35202090, 2022). "Research using transgenic mice with deficiency in Nos2, which encodes iNOS, showed increased vulnerability to infection by Mtb." (PMID 36295834, 2022). "A subsequent study confirmed that such was the case during the early time points of infection, and that at later stages NOS2-deficient mice were even more resistant to infection." (PMID 34832521, 2021). "Rats deficient in NOS2 are susceptible to L. amazonensis infection even though their immune response to infection is still strong." (PMID 34777283, 2021). "Nevertheless, a more complex role for NOX2 and NOS2 during in vivo infections has emerged which associates them with a role in host immune tolerance." (PMID 33194845, 2020). "NO is produced by the activity of an enzyme, inducible nitric oxide synthase (iNOS/NOS2), the expression of which is commonly induced following pathogenic infections." (PMID 33680983, 2020). "Regulatory variants acting prior infection or during infection map in different gene regions (e.g., NOS2), suggesting that infection status alters gene regulatory regimens." (PMID 31417551, 2019). "Nonetheless, the same NOS2 alleles (e.g., rs6505469) were also associated with higher incidence of asymptomatic infection among apparently healthy individuals." (PMID 31417551, 2019). "M-MDSC acted as target cells for mycobacterial growth, created an inflammatory milieu prone to cause T cell suppression and aggravated the infection by the expression of Nos2 and Arg1." (PMID 30386330, 2018). "In fact, the infection with La-arg− resulted in lower levels of miR-294-3p and miR-721, which can be associated with higher levels of Nos2 mRNA, NOS2 and NO production in infected macrophages, all associated with a lower infectivity." (PMID 28276497, 2017). "Although M. tuberculosis strain BTB 02-171 induces strong Nos2 expression early after in vivo infection, this strain still causes severe disease, as shown by increased bacterial loads and enhanced lung pathology." (PMID 27849167, 2016). "This acute mortality was also associated with increased IFN-γ production and NOS-2 activity, suggesting that AAMs are critically involved in the suppression of highly pathogenic type-1 immune responses during infection with S. mansoni." (PMID 25211233, 2014). "Previous work has shown that mice deficient for NOS2 had impaired clearance of Pseudomonas from the lung 18 h after infection." (PMID 24595185, 2014). "TNF and Nos2 expression appear to be critical for limiting Salmonella growth in mice, as evidenced by the marked susceptibility of p40−/− mice to infection." (PMID 22624013, 2012). "•NO was found to be crucially important in a variety of infections, however, NOS2-deficient animals are less susceptible than ifn-γ KO to most microorganisms studied." (PMID 22348160, 2012). "Whereas K. pneumoniae infection promoted NOS2 gene expression, infection by A. fumigatus caused increased Arg1 expression in the lung." (PMID 21246055, 2011). "The expression levels of genes encoding TNF-α, IFN-γ and NOS2 in the lungs of mice treated with TN3-19.12 at 28 days post-infection, were significantly reduced compared to the control IgG1 treated animals." (PMID 21364878, 2011).
infection (continued). "Whether the increased expression of Arg2, Nos2, SpmS, and Mcp-1 in putrescine supplementation in infected macrophages is associated with macrophage polarization during infection warrants further investigation." (PMID 37000792, 2023). "NOS2-deficient macrophages were unable to contain the infection despite IFN-g stimulation." (PMID 35269694, 2022). "This is remarkably different to infection of NOS2 deficient mice with other M. avium subspecies." (PMID 32408806, 2020). "However, infection with La-arg- induces NOS2 expression and the production of NO, causing a lower infection index and blocking miRNA expression." (PMID 29077741, 2017). "Overall, EhLPPG induced the strongest infection-and treatment-specific increases in mRNA encoding protective cytokines (Il-1β, 2.7 ± 0.47 [p = 0.018]; NOS2, 4.9 ± 0.3 [p > 0.0001]); however, it had only a moderate effect on mRNA encoding non-protective cytokines (Il-10, 2.5 ± 1.2 [ns])." (PMID 28842620, 2017). "Additionally, compared with the less virulent laboratory strain H37Rv, Nos2−/− mice showed earlier susceptibility to BTB 02-171 infection that correlates with earlier induction of elevated levels of Nos2 expression following infection with this strain." (PMID 27849167, 2016). "Although we cannot completely exclude the hypothesis that elevated Nos2 expression can contribute to disease severity during infection with M. tuberculosis strain BTB 02-171, mice deficient for NOS2 were extremely susceptible to infection with this strain." (PMID 27849167, 2016). "As Nos2 was shown to be dispensable for controlling S. Tm during the initial days of infection, we hypothesized that the Nos2-deficient mice should restrict gut luminal S. Typhimurium loads as efficiently as the wild type animals." (PMID 25522364, 2014). "In addition, mice deficient for NOS2 are more susceptible to infection with Leishmania, compared to their littermate controls, as well as macrophages derived from these mice." (PMID 22523640, 2012). "Importantly, blockade of NOS2 action was associated with enhanced viral loads after infection, and more severe disease manifestation, even in the presence of high levels of IFN-γ." (PMID 22206036, 2011). "Of note, neuroinflammation and cognitive deficits resulting from infection may be caused, at least in part, by the generation of NO by NOS2, as NOS2 knockout animals were protected from sustained microglial activation, expression of proinflammatory factors in brain, and behavioral deficits." (PMID 37277738, 2023). "Based on the latest human genetic leprosy susceptibility research and mouse infection models, we generated a double knockout mouse strain (10NOS2−/−) which has deficiencies in two key immune factors, interleukin-10 (IL-10) and inducible nitric oxide synthase (NOS2)." (PMID 25210773, 2014). "In contrast, HIF-1α-specific target genes including Nos2, Pgk1 and Ldha are dramatically increased upon infection, and these are predominantly expressed in monocyte-derived macrophages." (PMID 40191198, 2025). "As the primary interface between the host and bacterial pathogen, proteomic analysis on colonic IEC identified infection-induced increases in proteins regulated by IFNγ such as NOS2, RegIIIγ, and major histocompatibility complex II (MHCII)." (PMID 39937862, 2025). "Conversely, the transient increase in Nos2 expression suggests a limited nitric oxide-mediated antimicrobial response during infection." (PMID 41258798, 2025). "Infection-induced increases in Nos2 expression at 10 and 29 dpi were significantly reduced in CP96345-treated mice." (PMID 39937862, 2025). "Gene expression analysis showed distinct metabolic shifts, including upregulation of arginase-1 (Arg1) and proline metabolism genes, with concurrent suppression of nitric oxide synthase 2 (Nos2) in the brain during the late infection phase." (PMID 41258798, 2025).
infection (continued). "RT-qPCR analysis demonstrated significant upregulation of M2 markers (Cd206 and Mr) following infection, with minimal changes in M1 markers (Cd86 and Nos2)." (PMID 40248690, 2025). "At 24 h post-infection, both the Nos2 gene and protein expression levels of iNOS were evaluated by RT-qPCR and Western blot, respectively." (PMID 40936901, 2025). "Strikingly, Ccr2−/− mice were highly susceptible and succumbed to infection beginning at 5 DPI, with all mice dying by 9 DPI, which is more severe than phenotype in Nos2−/− mice." (PMID 38352492, 2024). "In macrophages, resident macrophages, and dermal dendritic cells, Nos2 and Arg1 involved in nitric oxide metabolism were upregulated genes after infection." (PMID 39536069, 2024). "In line with our in vitro findings, peritoneal macrophages collected from Lysm-cre/Fam96afl/fl mice 6 days post-infection expressed relatively lower levels of Tnf-α and Nos2 compared to the controls." (PMID 38713713, 2024). "In conclusion, our results highlight the important role of L-arginine metabolism through NOS2 and Arg-1/2 during infection with T. cruzi." (PMID 39452749, 2024). "Our results showed that T.mu-colonized mice upregulated intestinal Nos2, Otc, and Ass1 expression, while downregulated Arg1 expression post infection, compared to the C. difficile-infected T.mu-free control mice." (PMID 38565558, 2024). "Strikingly, Ccr2–/– mice were highly susceptible and succumbed to infection beginning at 5 DPI, with all mice dying by 9 DPI, which is more severe than the phenotype in Nos2–/– mice." (PMID 39541153, 2024). "Once we determined that infection with the T. cruzi isolates inhibited NOS2 and Arg-2 expression in neonatal mouse cardiomyocytes, we evaluated if this inhibition at the protein expression level paralleled enzyme activity." (PMID 39452749, 2024). "NOS2 is essential for resistance to M. tuberculosis infection in B6 mice and mice that lack the NOS2 gene succumb to infection 4-5 wpi30." (PMID 38977711, 2024). "When neonatal mouse cardiomyocytes were infected with T. cruzi isolates and stimulated with TNF-α + IFN-γ, there was an important decrease in the expression and activity of NOS2, and the effect of the infection with both isolates was similar." (PMID 39452749, 2024). "On the other hand, infection of cardiomyocytes with either QRO or CI2 isolates and further stimulation with TNF-α + IFN-γ inhibited NOS2 expression and NO production, leading to amelioration of infection." (PMID 39452749, 2024). "A striking increase in NOS2 mRNA levels is visible directly after the end of the active infection phase (3h of bacterial exposure), with a consecutive upregulation thereafter." (PMID 39691712, 2024). "NOS1 and NOS3 are constitutively expressed, and produce small quantity of NO, while NOS2 generates NO for extended periods of time, at high concentrations, being key as regulator and effector during inflammation and infection." (PMID 38841361, 2024). "We expected to find a decrease in NOS2 due to the infection since T. cruzi needs to down-regulate this enzyme on its behalf to prevent the action of trypanocydal NO and its derivatives." (PMID 39452749, 2024). "The NOS2 expression by these different cell types correlated with their degree of infection (r = 0.98)." (PMID 38977711, 2024). "Along the course of infection, there was a reduction in the expression of M1 markers like Nos2, Cd40,Cd86, Tnfa, Nfkb2, Il6 and a corresponding increase in the expression of the M2 markers such as Arg1, Ccl17, Cd206, IL4ra with an exception of Tgfb." (PMID 39693143, 2024). "Regarding the expression of genes related to macrophage polarization, putrescine supplementation during infection increased the expression of Nos2 and Mcp1 independently of L-arginine supplementation." (PMID 37000792, 2023). "Nos2 and Il1β mRNA levels increased upon S. japonicum infection, reached a peak at 6 weeks post‐infection (p < 0.05), and then decreased." (PMID 37430471, 2023).
infection (continued). "The involvement of Nos2 in the response to infection has been identified and characterized in various teleost species." (PMID 37446358, 2023). "Consistent with reduced IFNγ expression, the mRNA induction of Nos2, Gbp1, Gbp2, Gbp4, Gbp5, Ido1 and Acod1 was severely impaired in the spleens of Myd88−/− mice after intraperitoneal infection." (PMID 36479617, 2023). "Our analysis showed that ΔsteE STm infection led to lower frequencies of RPM, Nos2+, Vcam1+, and Trem2+ MΦs compared to WT STm infection." (PMID 36608122, 2023). "Macrophage Nos2 levels increased under L-arginine deprivation and also under supplementation with put+ or arg+/put+ at 4h of infection compared to arginine, spermidine, and spermine supplementation." (PMID 37000792, 2023). "Macrophages and supernatants were collected after different times (0h, 4h, 12h, 24h and 48h) of B. abortus-infection, and mRNA expression of macrophage M1 (Tnfα, Nos2 and Il1β) and M2 (Tgfβ, Arg1, Il10) polarization marker genes were detected by RT-qPCR." (PMID 37325614, 2023). "We have compared 4–5-week-old male C57BL/6 mice with NOS2-/- mice for pathological outcomes on RSA59 infection." (PMID 36966345, 2023). "The expression levels of proteins, of NOS2, and the concentration of NO in the liver were detected at three, five, and seven days after infection with L. monocytogenes." (PMID 37298614, 2023). "In contrast to our expectations, we did not observe a correlation between a reduction in Arg1 and an increase in Nos2, reflecting in changes in NO production upon putrescine supplementation during infection." (PMID 37000792, 2023). "RSA59 infection in C57BL/6 WT mice led to upregulation of NOS2 mRNA and protein at the acute phase, i.e., day 5/6 p.i. confirming its role in RSA59-induced acute neuroinflammation." (PMID 36966345, 2023). "As early as 12 hpi we observed modest Nos2 expression, which became strongest at 3 dpi and continued throughout the infection." (PMID 37865673, 2023). "Levels of nos2 mRNA were strongly induced with infection over the first 24 hours and continued to increase thereafter, and imatinib limited such increases." (PMID 37200402, 2023). "The current study was thus initiated to revisit the role of NOS2 in demyelination using MHV-RSA59 infection as the model." (PMID 36966345, 2023). "In the current study, we showed that NOS2 expression was upregulated at the acute phase of RSA59 infection and its absence led to more severe clinical disease score as compared to WT mice." (PMID 36966345, 2023). "Firstly, we detected the expression of ARG1 and NOS2, the well-known macrophage phenotype M2 and M1 markers, in lung homogenate on day 3 post-infection by western blotting." (PMID 37704783, 2023). "NOS2 also plays a major role in placental blood flow, response to infection, and development of diabetic embryopathy." (PMID 36672920, 2023). "IL-1β induces NOS2 and NO production and resistance to infection in C57BL/6 BMDM infected with L. amazonensis, and transcriptome data showed downregulation of Il1b in L. amazonensis infected BALB/c-BMDM." (PMID 37000792, 2023). "Accordingly, Nos2 activation in the immune response to infection is observed in various teleost species." (PMID 37446358, 2023). "NO is produced by induced nitric oxide synthase/nitric oxide synthase 2 (iNOS/NOS2) in vascular endothelial cells and on the one hand dilates blood vessels and on the other hand participates in the immune response to cancer and infection." (PMID 35204295, 2022). "The expressions of il10, nos2 and the ISGs isg15, and mx1 were only upregulated in tlr2−/− macrophages following infection, indicating that TLR4 controls the levels of these M(Kp) markers." (PMID 36337046, 2022). "Findings of the CDC1551-infected Nos2−/− mice by the i.c.vent route were successfully reproduced in a separate experiment evaluating the M.tb strain and route of infection for the CNS-TB model." (PMID 35073927, 2022).
infection (continued). "miR-294 and miR-301b inhibition at 4 h of infection tended to increase Nos2 levels and reduced them at 24 h." (PMID 35202090, 2022). "On the other hand, the Slc7a1 L-arginine transporter was downregulated during the infection, and Nos2, Arg1, Odc1, and Slc7a2 were expressed at similar levels in uninfected macrophages." (PMID 35202090, 2022). "Epithelial Paneth cells produce and release α-defensins, an AMP that, in combination with NO from nitric oxide synthase (NOS2), acts to control Giardia burden and eliminate infection." (PMID 36211380, 2022). "We also observed decreased levels of those miRNAs target genes during infection, such as Cationic amino acid transporters 1 (Cat1/Slc7a1), Cat2/Slc7a22 and Nos2; genes were upregulated in LPS stimuli." (PMID 35202090, 2022). "Violin plots show that Kp52145 infection increased the levels of the M(Kp) markers arg1, il10, chi3l1, ido, pparγ, mrc1, nos2, isg56 and il1rn (Fig EV5A–E)." (PMID 36337046, 2022). "The transcriptional changes upon infection were dominated by Ifng and its downstream genes (e.g. Stat1, Irf1, Fcgr1, Nos2, Cxcr3) and IFN-dependent CXCR3 binding chemokines (e.g. Cxcl9, Cxcl10)." (PMID 36400767, 2022). "In macrophages, the up-regulation of NOS2 and NO production during the initial steps of infection exerts robust leishmanicidal activity." (PMID 35925884, 2022). "Infection with L. amazonensis induces miR-30e and miR-302d, which regulate Nos2 and NO levels and miR-294 and miR-302d, which regulate Tnfa levels, in BALB/c-BMDM." (PMID 35202090, 2022). "In contrast, the expression of nos2, and il12 were upregulated following infection (EBI BioStudies accession number S‐BSST892)." (PMID 36337046, 2022). "The expression of miR-294-3p and miR-721 is increased in L. amazonensis-infected macrophages up to 48 hours following infection, targeting NOS2 mRNA; reduced NOS2 expression and NO production support the L. amazonensis infectivity." (PMID 35925884, 2022). "infection of Nos2−/− mice with either M.tb H37Rv or CDC1551 resulted in a high mortality (67% and 60%, respectively), similar to human CNS-TB, H37Rv is superior to CDC1551 as the murine CNS-TB model for two reasons." (PMID 35073927, 2022). "Our results point to a crucial role of TbISP2 for parasite virulence in mice, contributing to the reduction of NOS2 expression by myeloid cells throughout infection, and to down-modulation of the generation of IFN-γ+ NK cells during early infection." (PMID 34153047, 2021). "Bacterial burden (CFU) in lungs of C57bl/6 (broken lines), and age-matched Nos2-/- (solid lines) mice infected with WT M. tuberculosis (blue) or M. tuberculosis Δrip1 (red) at the indicated times (days) post infection." (PMID 34003742, 2021). "In contrast to wild-type BMDMs, IL-1β secretion was significantly up regulated in Nox2-/-, Nos2-/-, and mCAT+/+ BMDMs during ΔpknF mutant infection." (PMID 34324582, 2021). "We found significantly higher Nos2 expression in the skin of iKIR-treated animals than mice treated with the scrambled peptide control at day 1 post-infection." (PMID 33690673, 2021). "Supportively, NOS2 expression in H9N2 virus or E. coli single infection group was moderately elevated compared to that of the mock group." (PMID 33968006, 2021). "The downregulation of those nuclear receptors probably contributes to the transcriptional induction of pro-inflammatory genes in the early innate immune response in the infection by L. infantum, such as Ifng, Nos2, and Tnf." (PMID 34281214, 2021). "M. avium displays increased virulence during infections in wild-type mice when compared to nitric oxide synthase (NOS2) knockout mice, despite of the subsequent action of inducible nitric oxide synthase (NOS2) to control bacterial replication." (PMID 34832521, 2021). "While DMOG increased both HIF-1α-specific targets Nos2 and Pgk1 in LysMCreARNTf/+ macrophages compared to untreated cells during infection, this effect was only significant for Nos2 expression." (PMID 34959539, 2021).